PAK4 (p21 (RAC1) activated kinase 4)
Diseases named in the same sentence as PAK4 in open-access papers (continued):
Sharing a sentence is not in itself a finding about the gene and the disease.
cancer (continued). "Accumulating evidence has confirmed the mediation of PAK4 in chemoresistance in various types of cancers." (PMID 26411419, 2015). "Up-regulation of Pak1 and Pak4 has also been observed in other human cancers, such as breast and colon cancers." (PMID 26218748, 2015). "P21-activated kinase 4 (PAK4), an effector of the Rho family protein Cdc42, is an important oncogene whose expression is increased in many human cancers and is generally positively correlated with advanced disease and decreased survival." (PMID 25975262, 2015). "Cytoplasmic Pak4 showed significantly lower expression in patients with late stage disease and cancers involving cervix (all P<0.05)." (PMID 26218748, 2015). "Up-regulation of Pak1 and Pak4 mRNA and protein expression was also found in cancer cell lines (HEC-1B, HEC-1A and RL95-2) compared with normal endometrial cells by qPCR and Western blot analysis, respectively." (PMID 26218748, 2015). "PAK4 activity is essential to support the anchorage-independent growth of cancer cells induced by Ras." (PMID 25093037, 2014). "In many cancer cell lines PAK4 was shown to be constitutively-active, and PAK4 and other members of this kinase family emerge as targets for the development of inhibitors for clinical use." (PMID 24840177, 2014). "PAK4 is also reported to be elevated in 78% of cancer cell lines and plays a role in focus formation." (PMID 23818969, 2013). "Strikingly, although apoptosis appeared to be minimal in the MDA-MB-231 cancer cells, apoptosis was markedly restored when Pak4 was knocked down." (PMID 23732710, 2013). "While there is limited reports showing PAK3 expression in cancers, PAK1 over-expression has been linked to ovarian, breast, bladder and lymph cancers, while elevated PAK2, PAK4 and PAK6 expression has also been observed in prostate cancer." (PMID 23818969, 2013). "Better understanding of the molecular mechanism by which Pak4 and other Pak kinases promote cancer will be important for designing the best possible inhibitors." (PMID 23326684, 2012). "PAK4 reportedly regulates many cellular functions, such as adhesion, migration, proliferation, and immune regulation; moreover, PAK4 can contribute to abnormal tumor vascularization and hypoxia in cancer." (PMID 40180890, 2025). "Among the PAK isoforms, PAK1 and PAK4 are the most extensively studied in cancers." (PMID 40943273, 2025). "By summarizing the functions of PAK4 in tumors and its existing small-molecule inhibitors, it may help us gain insights for the development of highly specific inhibitors that target its cancer-promoting functions." (PMID 40332759, 2025). "The current finding that PAK4 KO increased cancer cell surface MHC I expression may serve as a potential mechanism for the induction of T-cell infiltration." (PMID 39941877, 2025). "In addition, the rapid development of resistance to PAK4 inhibition by cancer cells remains another challenge to overcome." (PMID 39941877, 2025). "In the realm of PAK group functionalities, we have elucidated the established correlation of PAK4 with various malignant neoplasms, as well as its roles in shielding cells from apoptosis, fostering cellular motility, and impeding adhesion and anchorage-independent proliferation." (PMID 40332759, 2025). "PAK4 inhibitors are considered to be promising targets for cancer therapy." (PMID 39337621, 2024). "In particular, it raises the question of whether it inhibits cancer cell growth via PAK4 inhibition, NAMPT inhibition, or both." (PMID 39337621, 2024). "Moreover, PAK4 has been suggested to be a molecule closely related to the immune evasion of cancers." (PMID 39273017, 2024). "Our results suggest that PAK4 inhibitors may have a more complex mechanism of action than previously understood, necessitating further exploration of how they influence cancer cell growth." (PMID 39337621, 2024).
cancer (continued). "Moreover, PAK4 has been suggested to be closely related to the immune evasion of cancers, and it has been shown that the suppression of PAK4 enhances the anticancer therapeutic efficacy of immune checkpoint inhibitors." (PMID 39273017, 2024). "p21-activated kinase 4 (PAK4) is a serine threonine kinase, the levels of which correlate with the progression of a variety of cancers and could serve as a prognostic marker." (PMID 39654621, 2024). "This suggests that UCHL1, SNRNP200, and PAK4 could serve as valuable prognostic markers, offering new insights into the progression and prognosis of this aggressive cancer subtype." (PMID 39199615, 2024). "In addition to KPT-9274, several other PAK4 inhibitors have also been shown to have growth-inhibitory functions in cancer cells." (PMID 39337621, 2024). "Pak4 has been previously reported to be highly expressed in various cancers." (PMID 38807162, 2024). "PAK4 and PD-L1 have been suggested as novel therapeutic targets in human cancers." (PMID 39273017, 2024). "Overexpression of PAK4 correlates with poor prognosis in some cancers." (PMID 39337621, 2024). "Several small molecule inhibitors targeting PAK4, such as ATP-competitive inhibitors like PF-3758309 and LCH-7749944, have shown promising effects in different cancers in preclinical models by inhibiting PAK4 activity and subsequently reducing tumor growth and metastasis." (PMID 39199615, 2024). "In contrast, strong PAK4 staining was observed in poorly differentiated carcinoma cells." (PMID 38890401, 2024). "PAK4 expression is negatively correlated with immune cell infiltration in other cancers." (PMID 38067120, 2023). "Studies in recent years showed that PAK4 inhibitors can inhibit its expression, thus preventing tumor growth, inducing tumor regression, and avoiding tumor cell metastasis, which has a good effect on the treatment of cancers." (PMID 36615619, 2023). "The prognostic impact of the expression of PAK4 and PHF8 might be associated with their role in cancer progression." (PMID 36980457, 2023). "The expression of PAK4 has been shown to be involved in cancer progression." (PMID 36980457, 2023). "Based on previous observations that cancer cells often overexpress PAK4 and exhibit altered metabolic flexibility, we hypothesized that PAK4 may regulate metabolic adaptation processes." (PMID 37591884, 2023). "Moreover, as more evidence emerges regarding the role of PAK4 in the immune evasion of cancer cells, research has evaluated the efficacy of a combination treatment of PAK4 inhibition and immune checkpoint inhibitors." (PMID 36980457, 2023). "PAK4 has been shown to promote cell proliferation and suppress apoptosis in many cancer models." (PMID 35920284, 2022). "Intriguingly, both RSK2 and PAK4 were highly expressed in multiple cancer types." (PMID 36045417, 2022). "p21-Activated kinase 4 (PAK4), one of the serine/threonine kinases activated by Rho-family GTPases, has been widely studied as an oncogenic protein that is overexpressed in many types of cancers." (PMID 35920284, 2022). "Thus, it makes sense that the PAK4 gene should be selected for preservation and amplification in cancers whose oncogenic signalling networks require this enzyme as a downstream effector." (PMID 35969127, 2022). "In addition to its various cellular functions, PAK4 has an important role in different cancers via activation of pathways such as the PI3K‐AKT signalling pathway." (PMID 34009729, 2021). "Increased PAK1 and PAK4 expression in ES is consistent with those seen in other cancer types." (PMID 36594908, 2021). "Several studies have reported that PAK4 could be regulated by many miRNAs in various cancers, including miR-485 and miR-199a-3p." (PMID 32041570, 2020). "Interestingly, pancreatic cell plasticity and cancer initiation induced by Kras is completely dependent on wild-type p110α, and PAK4 interacts with p85α can affect the migration of PDAC cells." (PMID 32333246, 2020).
cancer (continued). "Therefore, PAK4 is regarded as an attractive therapeutic target in diverse types of cancers, prompting the development of PAK4-specific inhibitors as anticancer drugs; however, these drugs have not yet been successful." (PMID 30755582, 2019). "PAK4 is activated through diverse signaling pathways in cancer." (PMID 30755582, 2019). "PAK4 also affects stemness and cancer resistance to endocrine therapies." (PMID 31416295, 2019). "Yet, the potential functional role of PAK4 during cancer development in vivo has remained unknown and our understanding of the PAK4 signaling pathways that affect tumorigenesis is so far sparse." (PMID 31399573, 2019). "PAK4 maintains cancer stem cell phenotypes through Stat3 signaling." (PMID 31658701, 2019). "Beyond that, our data show that PAK4 inhibition almost invariably arrests cancer cell proliferation, while inducing additional senescence-like features (including morphological changes, increased SA-β-gal activity, and gene expression changes indicative of a senescent-like phenotype)." (PMID 31399573, 2019). "Thus, eleven out of fourteen cancer cell lines here examined exhibited increased SA-β-gal activity upon PAK4 knockdown." (PMID 31399573, 2019). "Development of specific inhibitors dissociating PI3K from PAK4 may represent a novel therapeutic modality in diverse types of cancers in which PI3K and PAK4 play a central role in progression." (PMID 30755582, 2019). "Based on accumulating evidence, PAK4 is an alternative target in mutant K-Ras-driven cancers." (PMID 30755582, 2019). "Therefore, our mouse model of conditional depletion of PAK4 in the mammary epithelium can be useful for testing potential in vivo functions of PAK4 in mammary physiology and diseases such as cancer." (PMID 31594963, 2019). "Finally, PAK4 protein is markedly overexpressed in all three cancer cell lines compared to hESO cells." (PMID 29983868, 2018). "Pak4 is overexpressed and/or activated in various human cancer cells." (PMID 28978098, 2017). "PAK4 is also overexpressed in other types of cancer, making it a promising drug target." (PMID 28198380, 2017). "PAK4 belonging to subgroup II of PAKs, is highly expressed in a variety of cancers." (PMID 28680855, 2017). "Also, filopodia formation was reported to be PAK4 dependent and we and others have previously shown that PAK4 promotes cancer cell migration." (PMID 29100370, 2017). "Additionally, the microRNA, mir-199a.b-3p, which is down-regulated in several types of aggressive cancer, was found to directly target PAK4." (PMID 28198380, 2017). "There results indicated that PAK4 has a clinical significance in cancer." (PMID 28440035, 2017). "In addition, we report a novel interaction between PAK4 and the CCT complex, a chaperonin that is essential for folding of the cytoskeletal proteins actin and tubulin and that is overexpressed in cancer (just like PAK4)." (PMID 29100370, 2017). "Importantly we also found that reduced PAK4 expression significantly reduced the level of cancer cell invasion in the HGF-mediated organotypic invasion assay." (PMID 28205613, 2017). "In the future, it would be important to determine whether inhibiting PAK4 simultaneously with different types of inhibitors, could result in even stronger inhibition of PAK4 and inhibition of cancer cell growth." (PMID 28198380, 2017). "As mutations of PAK4 and RYR1 tend to co-occur in HGSOC, and the two genes might interact, we hypothesize that caffeine, a cancer drug that targets RYR1, may represent a useful intervention strategy to treat HGSOC patients with PAK4 mutations." (PMID 27788148, 2016). "PAK4 overexpression has been reported in many human cancers; however, its expression in NSCLC remains unclear." (PMID 25975262, 2015). "All cancer cell lines expressed high levels of PAK4 protein compared with the HBE cell line." (PMID 25975262, 2015). "Besides, PAK4 has been recognized to modulate the cancer migration and invasion via interacting with Met or with DGCR6L." (PMID 26411419, 2015).
cancer (continued). "Although PAK4 is an important oncogene in many cancers, the role of PAK4 in NSCLC remains obscure." (PMID 25975262, 2015). "Upregulated PAK4 promotes cell migration in several cancers." (PMID 25975262, 2015). "Furthermore, it was also demonstrated that PAK4 prevented cancer cells from undergoing apoptotic cell death by inhibiting the activation of caspases-3/8/7 and subsequently leading to PARP1 cleavage." (PMID 25238288, 2014). "PAK4 is overexpressed in various cancer cell lines and Ras related tumors." (PMID 25093037, 2014). "Its binding to Cdc42 is important for establishing cell polarity, and one possibility is that Pak4 may interfere with the Cdc42:Par6 interaction when it is overexpressed, thereby disrupting cell polarity in cancer." (PMID 23326684, 2012). "For example, Pak4 has an important role in suppressing apoptosis, which could be directly related to its role in cancer, but under some conditions this occurs completely independently of Pak4's kinase activity." (PMID 23326684, 2012). "In this case, drugs designed specifically to block Pak4 kinase activity alone may be incompletely effective in some types of cancer, and new strategies for blocking Pak4 should be investigated." (PMID 23326684, 2012). "Pak4 has a great potential as a druggable target for the treatment of breast and other cancers." (PMID 23326684, 2012). "However, how PAK4-associated autophagy affects PDA cell survival and immune response remains unknown, given autophagy can play different roles in cancer cells." (PMID 39941877, 2025). "Similarly, PAK4 orchestrates pivotal cellular processes, regulating proliferation, survival, invasion, metastasis, epithelial–mesenchymal transition, and drug resistance, thereby propelling the overarching progression of cancer." (PMID 40332759, 2025). "The results from these studies suggest that PAK4 may be a promising target for cancer treatment." (PMID 39337621, 2024). "Genes containing AS events associated with overall survival are known components of cancer-related pathways, including regulation of transcription (E2F4, ZNF730, GPBP1, POLR2J, SP2, and CIART), cell cycle (E2F4 and GTSE1), or cell-cell adhesion (CEACAM1, MMP14, EPS8L2, AP3D1, AFDN, and PAK4)." (PMID 35044822, 2022). "Hence, our results add a further facet to the role of PAK4 in directing cancer cell motility." (PMID 35883575, 2022). "With this in mind, we tested if PAK4-inhibition could restore senescence in established cancer." (PMID 32158912, 2020). "Rearrangements of actin filaments are of great importance for both normal cell migration and cancer cell migration/invasion, and indeed, several actin-regulating proteins are implicated in cancer cell migration, two of which are now known to bind CCT: the p21-activating kinase PAK4 and gelsolin." (PMID 30506376, 2019). "This suggests that PAK4 overexpression may overcome the OIS barrier to cancer." (PMID 31399573, 2019). "In addition, Sox2, PAK4 and c-Myc are regulators of cancer cell proliferation." (PMID 29137251, 2017). "Moreover, elevated expression of PAK4 promotes cancer progression in vitro and in vivo." (PMID 28407679, 2017). "Studies on prostate cancer cells proved that targeting the RAC2/PAK4/LIMK1/cofilin pathway impeded cancer progression and reinstated arsenic-induced cancer cell apoptosis." (PMID 40072059, 2025). "Given that cancer cell autophagy was also found to degrade cell surface MHC I in PDA, we further assessed the effect of PAK4 inhibition on autophagy, and its relation to the expressions of MHC I, MHC II, and PDL1 in human PDA cell lines." (PMID 39941877, 2025). "Our work raises important questions about the link between PAK4 and NAMPT inhibition in cell growth, emphasizing the need for further research to identify the most effective inhibitors in cancer treatment." (PMID 39337621, 2024). "PAK4 inhibitors, such as KPT-9274 and PF-03758309, have been shown to reduce tumor growth in various cancer cell lines and in animal studies." (PMID 39337621, 2024).
cancer (continued). "In order to investigate into role of Pak4 in different cancers, we used TIMER database to probe into differential expression of Pak4 at pan-cancer level." (PMID 38807162, 2024). "Serine/threonine kinase p21-activated kinase 4 (PAK4), belonging to the PAK family (PAK1-6), is best known for its regulation of cytoskeletal changes, migration, and cancer cell proliferation and invasion." (PMID 37591884, 2023). "The viability, invasion, and migration of cancer cells are reduced by the KPT-9274, which is a hybrid inhibitor of NAMPT and serine/threonine–p21-activated kinase 4 (PAK4)." (PMID 37175631, 2023). "In the survival analysis of pan-cancer patients, high expression of PAK1, PAK2, PAK4, and PAK6 as well as the low expression of PAK7 was mainly associated with poor prognosis of tumor patients." (PMID 36064705, 2022). "P21 activated kinase 4 (PAK4) and Breast cancer anti-estrogen resistance 3 (BCAR3) have been reported to be involved in numerous aspects in tumorous progression." (PMID 35842733, 2022). "Related to these findings, PAK4 is known to activate canonical NF-κB signalling (essentially via RELA, NF-κB p65 subunit) in cultured cancer cells, which contribute to cell proliferation and cell migration." (PMID 35920284, 2022). "These genetic data are consistent with PAK4 being more functionally relevant than PAK5 and PAK6 for these cancers, even though the three enzymes have similar domain architectures and intrinsic substrate specificities." (PMID 35969127, 2022). "Mechanism study confirms that 7 inhibits phosphorylation of PAK4 and its downstream proteins LIMK1 and Cofilin, and mitigates cancer cell migration and invasion." (PMID 36105226, 2022). "Because PAK4 has been well summarized, including its signaling, regulation, and specificity 8, here, we focus our discussion on PAK1 in cancer." (PMID 32863957, 2020). "Aberrant expression of PAK4 and NAMPT is driven by a variety of genetic changes play a critical role in the survival of several cancers." (PMID 31795447, 2019). "The data presented here complements previously published studies with other cancer types and suggests a global involvement for PAK1 and PAK4 in cancer invasion at least in vitro." (PMID 27765920, 2016). "Interestingly, a number of findings suggest that PAK4 may be involved in cancer progression." (PMID 26554417, 2015). "For this, we primarily focused on two known downstream mediators of PAK4, Akt and ERK, which are also shown to regulate NF-κB in cancer cells." (PMID 25238288, 2014). "However, whether PAK4 plays a role in chemoresistance in cancer cells remains undefined." (PMID 27919028, 2014). "PAK4 knockout (KO) suppressed the cancer cell proliferation of MiaPaCa-2 cells (MiaPaCa-2 PAK4 KO8 was used in all assays) but not of PANC-1 cells." (PMID 39941877, 2025). "We thought that PAK4 inhibition could affect the expression of immune markers, especially MHC I, on the cancer cell surface to stimulate T-cell infiltration." (PMID 39941877, 2025). "PAK4 was reported to play a role in PDA cell apoptosis, cell cycle arrest and cancer cell stemness." (PMID 38797819, 2024). "Therefore, when considering the role of PAK4 in cancer progression through regulating the cancer microenvironment and the role of PD-L1 in the immune evasion of cancer cells, there might be a close relationship between PAK4 and PD-L1 in cancer progression and resistance to anticancer therapies." (PMID 39273017, 2024). "Based on the available literature, there are no other reports on the involvement of ER stress in high PAK4 expression-induced cisplatin resistance in malignant tumors." (PMID 38238316, 2024). "Similarly, there are reports indicating that PAK4 and PHF8 are expressed in both the nuclei and cytoplasm of cancer cells." (PMID 36980457, 2023).